NPC2 (NPC intracellular cholesterol transporter 2)
Diseases named in the same sentence as NPC2 in open-access papers (continued):
Sharing a sentence is not in itself a finding about the gene and the disease.
infection (16 papers, 2012 to 2025). The state of being infected such as from the introduction of a foreign agent such as serum, vaccine, antigenic substance or organism. "We have identified an NPC2 deficient cell line (NPCD55) that loses expression of NPC1 upon infection by HIV-1." (PMID 22273177, 2012). "For example, HYPK, which encodes a chaperone‐like protein associated with the regulation of cell death and apoptosis, and NPC2, which encodes a cholesterol transporter that is differentially expressed during disease infection, were detected as candidate genes under selection in the Northern region." (PMID 37780082, 2023). "We analysed the differential expression of NPC2 genes in uninfected and infected mosquito midgut and salivary gland tissues to understand the potential role of NPC2 proteins during infection." (PMID 38338961, 2024). "This indicates that progeny virions binding NPC2 protein can promote its infection, producing a cascade amplification effect." (PMID 35867410, 2022). "After 96 h of infection, we found that BV-binding NPC2 protein promotes infection in BmE and NPC2-null cells." (PMID 35867410, 2022). "The varied expression of the 20 mosquito NPC2 genes during different infections may suggest that each of these genes has some role in arboviral infections." (PMID 38338961, 2024). "To assess whether this is also true in the adult intestine, where the expression of Npc2 genes varies in different cell types and upon infection challenge, we performed RT-qPCR of control and ISC/EB-specific Npc2c-silenced adult midguts in uninfected conditions." (PMID 37887409, 2023). "We next determined whether binding to NPC2 affects progeny virion infection." (PMID 35867410, 2022). "By silencing any of AGAP006268 (peritrophin), AGAP006972, AGAP002848 (NPC-2 related), or AGAP002851 (NPC-2 related), the number of P. falciparum oocysts in mosquito midguts significantly increased compared to that of the control, suggesting they protected mosquitoes from infection." (PMID 32868841, 2020). "MDMs trained with BS and BL restored their ability to upregulate NPC2, MAP1LC3, and ATG16L1 after infection with M. tuberculosis." (PMID 41488622, 2025). "At 96 h post-infection, CYP307A1, NPC2, and HEXB are significantly upregulated compared to 72 h, indicating a shift in immune strategy." (PMID 40003829, 2025). "In summary, the NPC2 genes AAEL004120, AAEL012064 and AAEL009556 are downregulated post all three (CHIKV, DENV1 and DENV2) infections, whereas AAEL009760 is upregulated post all three infections." (PMID 38338961, 2024). "Comparisons between latent and active infection also showed a similarly low variation of AUROC values (DOCK9: 0.86–0.95; EPHA4: 0.91–0.96; NPC2: 0.8 –0.98)." (PMID 34685683, 2021). "These observed differential expression profiles of NPC2 genes may be due to either viral serotypes (DENV1 vs. DENV2), distinct mosquito strains (Thailand vs. Chetumal) or even different time points post infection (4-dpi vs. 14-dpi)." (PMID 38338961, 2024). "The fact that the NPC2 gene is significant and essential for CHIKV replication in humans and is significantly upregulated in the mosquito midgut after infection implies that an evolutionarily conserved mechanism may be at play and presents possible therapeutic opportunities in clinical treatment." (PMID 31167461, 2019). "Moreover, up-regulation of NPC2, with consistent changes in median expression, was observed in active disease (G.IV, p ≤ 0.001) compared to rCt with high (G.III, p < 0.05) or low-to-moderate (G.II, p = 0.06) probability of infection." (PMID 27826286, 2016).
neurological disease (4 papers, 2013 to 2024). "NPD type C is a neurologic disorder due to mutations in the genes NPC1 or NPC2, causing a defect of cholesterol trafficking and esterification." (PMID 38397448, 2024). "However, NPD type C is a neurological disorder caused by mutations in the NPC1 or NPC2 genes, leading to defects in cholesterol trafficking and esterification." (PMID 38397448, 2024). "Further, many unique genetic interactions of btn1102–208del correspond to conserved human orthologues, including genes related to eye and neurological diseases, for example, npc2 (Niemann–Pick C disease), linking these diseases with the pathogenesis of CLN3 disease." (PMID 33737578, 2021).
hereditary disease (3 papers, 2017 to 2023). A disease that is caused by genetic modifications where those modifications are inherited from a parent's genome. "Niemann-Pick type C2 (NP-C2) disease is a rare hereditary disease caused by mutations in the NPC2 gene." (PMID 33924575, 2021). "Niemann-Pick type C (NP-C) disease is a hereditary disease caused by mutations in the NPC1 or NPC2 gene." (PMID 33924575, 2021).
bacterial infection (2 papers, 2018 to 2025). "Initially, both vibrios elicited a proteomic response related to bacterial infection and immunity (e.g., ADAM10, RAPTOR), followed by an increase of lysosomal and endocytic proteins (e.g., NPC2) after 60 min." (PMID 40576359, 2025).
metabolic disorder (2 papers, 2023 to 2025). "Niemann–Pick disease (NP) type C is an autosomal recessive metabolic disorder caused by mutations in the NPC1 or NPC2 gene." (PMID 37458497, 2023).
adenocarcinoma (1 paper, 2015). A common cancer characterized by the presence of malignant glandular cells. "Based on our present study, we hypothesise that human lung AAH lesions, the precursors for adenocarcinomas, may respond to chemopreventive interventions targeting the microenvironment with CCR1 inhibitors, NPC2 protein itself or chemicals that up-regulate NPC2 expression." (PMID 26183450, 2015).
autosomal recessive inherited disease (1 paper, 2021). "It is an autosomal recessive inherited disease that results from mutations in the NPC1 or NPC2 genes." (PMID 34596813, 2021).
infectious disease (1 paper, 2021). A disorder directly resulting from the presence and activity of a microbial, viral, or parasitic agent in humans. "In addition, NPC2 plays a significant role in other infectious diseases, for example, upregulation of NPC2 is crucial for viral replication in Chikungunya, Zika, West Nile and Dengue infections." (PMID 33482742, 2021).
psychiatric disease (1 paper, 2023). "Niemann-Pick type C (NPC, ORPHA: 646) is a neuro-visceral, psychiatric disease caused predominantly by pathogenic variants in the NPC1 gene or seldom in NPC2." (PMID 38002933, 2023).
NPC2 also shares sentences with these, for which no sentence is quoted: Niemann-Pick disease, type C2 (13 papers); Niemann-Pick disease, type C1 (4); cognitive decline (3); COVID-19 (3); mucolipidosis type IV (3); sphingolipidoses (3); cognitive deficits (2); colon polyps (2); lung adenoma (2); Lysosomal disease (2); mucopolysaccharidoses (2); neurodegenerative disease (2); Pick disease (2); progressive supranuclear palsy (2); tuberculosis (2); amyotrophic lateral sclerosis (1); Anxiety (1); basal cell carcinoma (1); bronchitis (1); ceroid lipofuscinoses (1); cholestasis (1); chronic hepatitis (1); chronic viral hepatitis (1); colorectal cancer (1); Crohn disease (1); cutaneous melanoma (1); Danon disease (1); developmental delay (1); Dysphagia (1); Dystonia (1).
A further 42 diseases each share a sentence with NPC2 in 1 paper.